IL1B (interleukin 1 beta)
Diseases named in the same sentence as IL1B in open-access papers (continued):
Sharing a sentence is not in itself a finding about the gene and the disease.
inflammation (continued). "ASI ameliorated indomethacin‐induced intestinal inflammation in rats by inhibiting the activation of NLRP3 inflammasome and reducing the release of IL‐1β and IL‐18." (PMID 40586619, 2025). "Tongxinluo also reduces vascular endothelial inflammation by inhibiting inflammatory factors such as TNF-α, IL-1β, and IL-6." (PMID 40761406, 2025). "Chronic systemic inflammation in IBD, driven by cytokines such as TNF-α and IL-1β, can impair myocardial structure and function." (PMID 40710377, 2025). "HA exhibits anti‐inflammatory properties by inhibiting pro‐inflammatory cytokines, such as interleukin‐1 beta (IL‐1β) and tumour necrosis factor‐alpha (TNF‐α), and modulating the activity of immune cells involved in joint inflammation." (PMID 39210692, 2025). "Proinflammatory cytokines such as IL-1β and TNF-α play a central role in the initiation and maintenance of cerebral inflammation." (PMID 40141795, 2025). "The secretion of IL-6, IL-1β, TNF-α and other inflammatory factors is usually significantly up-regulated in animal models of intestinal inflammation." (PMID 40746956, 2025). "Compared to HFD‐fed WT mice, HFD‐fed Nod1−/− mice exhibited increased lung inflammation, as evidenced by higher neutrophil MPO expression and activity and elevated secretion of the cytokines TNF‐α, IL‐1β, and IL‐6." (PMID 40616268, 2025). "Specifically, we observed that miR-425a-5p overexpression effectively reduced pro-inflammatory cytokine production (IL-1β, IL-6, and TNF-α) in LPS-stimulated AC16 cardiomyocytes and ameliorated cardiac inflammation in the EAM mouse model." (PMID 40433545, 2025). "The concentrations of IL‐1β and RANTES were reduced by reticuline in the LFD‐HDM group, suggesting that reticuline suppressed both type 2‐low neutrophilic airway inflammation and type 2 eosinophilic airway inflammation." (PMID 38286741, 2024). "As expected, β-glucan treatment remarkably reduced neutrophil numbers in BALF and lung tissue, M. pneumoniae burden and LDH levels in BALF, and the levels of proinflammatory cytokines (IL-1β, IL-6, and TNF-α), which led to the remission of lung inflammation." (PMID 39499730, 2024). "IL-33 orchestrates tissue remodeling and immune response in chronic airway inflammation through both TH2 (initiated by ILC2 matured by IL-33) and TH17 (via IL-1β and IL-6 derived from IL-33-matured DCs) immune responses." (PMID 39244793, 2024). "PNFS at a concentration of 200 μg/mL downregulated the production of the inflammatory factors IL-1β and TNF-α to close to that of the control group in the UVB-induced inflammation model, indicating that PNFS can improve skin inflammation." (PMID 36903661, 2023). "IL-17 interacted with TNF-α, IL-1β, IFN-γ, and GM-CSF to exert synergistic activity on inducing inflammatory responses in chronic inflammation." (PMID 36728426, 2023). "In a carrageenan-induced paw inflammation model, the CB2 agonist GW405833 decreased serum concentrations of TNF and IL-1β." (PMID 37891972, 2023). "BLM induces pulmonary inflammation and PF within a short time, while BLM administered intratracheally up-regulates fibrotic factor levels, like IL-1β, IL-6, TNF-α, and TGF-β, etc.." (PMID 37160579, 2023). "During vascular inflammation, pro-inflammatory cytokines, such as monocyte chemoattractant protein-1 (MCP-1), Interleukin-1 β (IL-1β), and Interleukin-8 (IL-8), play critical roles in the recruitment of monocytes to endothelial cells at inflammation sites." (PMID 37764491, 2023). "In our study, YCF treatment significantly inhibited pulmonary inflammation in silica-exposed rats, by reducing inflammatory cell infiltration, and decreasing the secretion of inflammatory chemokines, including TNF-α, IL-1β, and IL-6." (PMID 37381044, 2023). "This is similar to LPS in liver inflammation, which is related to the activation of inflammasome nod-like receptor protein 3 (NLRP3) and the production of interleukin (IL)-1β through activation of the nuclear factor-κB (NF-κB) pathway." (PMID 37744692, 2023).
inflammation (continued). "Animal models of lipopolysaccharide-induced amniotic inflammation showed increased mRNA expression of inflammatory-related genes (NLRP3, Caspase-1, IL-1β), and higher concentrations of NLRP3 protein in fetal membranes and deciduae than before preterm delivery." (PMID 37571360, 2023). "Our results show an upregulation of NLRP3 in the well-established in vitro model for chronic muscle inflammation, as used for IBM upon stimulation with IL-1β and IFN-γ for 24 h, 48 h, and 72 h, creating a proinflammatory milieu." (PMID 37445853, 2023). "Our study showed that IL-10 treatment significantly decreased TNF-α infiltration and the expression of IL-1β, IL-6, IL-8, and TNF-α in Ang II-induced vascular inflammation." (PMID 35528508, 2022). "In the rat model, TQ was found to decrease interleukin-1β (IL-1β), IL-6, IFN-β, TNF-α and prostaglandin (PGE), which prevent pulmonary inflammation." (PMID 36558399, 2022). "Our results showed that exosomes and miR-150 partially attenuated lung inflammation, including total cells, neutrophils, macrophages, TNF-α, IL-6, and IL-1β." (PMID 34750610, 2022). "Chronic intestinal inflammation is closely related to the expression of pro-inflammatory factors such as TNF-α, IL-1β, IL-6 and IL-8." (PMID 36185671, 2022). "Andrographolide significantly mitigated lung inflammation in mice with CS-induced ALI and reduced the total number of inflammatory cells, neutrophils, and inflammatory mediators, such as IL-1β, IP-10, MCP-1 and KC, in BALF." (PMID 36238575, 2022). "Under such conditions, monocytes, macrophages, IL-6, IL-1β, and TNF-α, which are involved in increasing oxidative stress and peripheral vascular inflammation, are likely to enhance subsequent progression of inflammation." (PMID 35370896, 2022). "Improve lung inflammation by inhibiting the excessive recruitment of M1 and M2 under TGF-β1 to achieve a therapeutic effect, reducing the levels of MCP-1, TNF-α, IL-1β, IL-6, IL-10,IL-13, and OSM." (PMID 34489700, 2021). "Together, our results suggest that the 5-/12-LOX-BLT1/2-linked cascade are necessary for the simulation of the NLRP3 inflammasome and IL-1β synthesis, thus contributing to HDM/LPS-induced neutrophil-dominant airway inflammation." (PMID 34064821, 2021). "Previous research has shown that IL-6, IL-1β, MCP-1, NF-κB, TNF-α, ICAM-1 and VCAM-1 are all involved in the process of vascular inflammation." (PMID 34830730, 2021). "For the investigation of the effect of GFDHP on airway inflammation, the counts of inflammatory cells (including total cells, white blood cells (WBC), lymphocytes, and neutrophils) and the levels of cytokines (IL-1β and IL-6) in BALF were detected." (PMID 34777538, 2021). "IL-1β in BALF was significantly increased in the CS group as compared with that in the RA group, indicating that the mice were induced acute lung inflammation after 3 days of CS exposure." (PMID 32903481, 2020). "The marked reduction of pro-inflammatory cytokines in the serum appears to be emerging as an important target for the treatment of intestinal inflammation, such as TNF-α, IL-1β, and IFN-γ." (PMID 33208178, 2020). "Our study complements the existing data by identifying IL-1β as a key regulator by suppressing HO-1 expression in BBB-ECs at a certain threshold, which results in increased autoimmune inflammation." (PMID 32651669, 2020). "T. cruzi infection induced chronic heart inflammation, demonstrated by a significant increase in cell infiltration, fibrosis, and production of the proinflammatory cytokines TNF-α and IL-1β." (PMID 32393497, 2020). "A reduction of IL-1β, TNF-α, and IL-6 and increased pulmonary inflammation was found when BCG was used to intravenously infect C57BL/6 diabetic mice." (PMID 32194998, 2020). "The results of Elisa (IL-6, MCP-1, TNF-α, and IL-1β) in the BALF and HE in the lungs of mice showed that Tre alleviated CS-induced pulmonary inflammation." (PMID 31947943, 2020).
inflammation (continued). "The gene expression of IL-1β, IL-6, and TNF-α in rat models of acute joint inflammation and in the cartilage of rat models of OA decreased significantly after LLLT (808 nm, 142 J/cm2) and laser irradiation (808 nm, 71 J/cm2), respectively." (PMID 32213810, 2020). "Rutin treatment in rats with cerulein-induced AP and fed on ethanol reduced pancreatic inflammation and modulated the NLRP3 inflammasome by attenuating the expression of ASC, caspase-1 and IL1β." (PMID 32751171, 2020). "Pro-inflammatory cytokines such as IL-1α, IL-1β, IL-2, IL-5, IL-6, IFN-γ, MCP-1, MIP-1α, MIP-1β and TNF-α are shown to play an essential role in inducing age-related chronic inflammation." (PMID 31181695, 2019). "The LentiSigirr transduction effectively dampened the enhanced LPS-induced lung inflammation phenotype observed in Usp13−/− animals, with reduced cellular infiltration and neutrophils, TNF-α, and IL-1β." (PMID 31204278, 2019). "We found that after unilateral DMV damage, the protective function of the vagus efferent nerve by Ach attenuated, esophageal inflammation aggravated, and the concentrations of the proinflammatory cytokines TNF-α, IL-6, and IL-1β significantly increased." (PMID 31281769, 2019). "There is a body of evidence supporting GM-CSF as an important mediator in lung inflammation by upregulating TLR2, TLR4, and CD14 expression, and by boosting IL-6 and IL-1β production from macrophages." (PMID 30013577, 2018). "The GPR55 inhibitor CID16020046 reduced TNF-α, IL-1β, IL-6, and COX-2 levels in a mouse model of intestinal inflammation." (PMID 30453998, 2018). "The intestinal inflammation is characterized by a Th1 and Th17-mediated responses with enhanced expression of TNF-α, IFN-γ, IL-1β, IL-12, IL-6, IL-10 and IL-1761." (PMID 29872077, 2018). "In the present study, both CSE and CS were able to decrease the LPS-induced hepatic inflammation in the mice via downregulation of TNF-α, IL-1β, COX-2, and iNOS." (PMID 28617322, 2017). "Consistently, clinical studies show increased IL-1β level in the serum and inflamed colonic tissues of IBD patients, and IL-1β levels are correlated well with the severity of intestinal inflammation and disease activity." (PMID 27965665, 2016). "In conclusion, FD attenuates BLM‐induced pulmonary inflammation and fibrosis through suppressing the activation of NALP3 inflammasome and the IL‐1β/IL‐1R1/MyD88/NF‐κB signalling pathway." (PMID 27306439, 2016). "In this study, macrophage-derived NLRP3 inflammasome was identified as a platform essential for a systemic response to TsV, resulting in PGE2, IL-1β and LTB4 production, lung inflammation and mortality." (PMID 26907476, 2016). "Intestinal inflammation in colitic controls was characterized by a marked increase in pro- and anti-inflammatory cytokines TNF-α, IFN-γ, IL-1β, IL-6, IL-12, and IL-10, compared to normal controls." (PMID 27293323, 2016). "This study demonstrated that FD, attenuates BLM‐induced pulmonary inflammation and fibrosis in mice via inhibiting the activation of NALP3 inflammasome and the IL‐1β/IL‐1R1/MyD88/ NF‐κB pathway." (PMID 27306439, 2016). "Consistent with worsened renal dysfunction, Ang II infusion in the ApoEKO mice exhibited exacerbation of kidney inflammation with enhanced expression of TNF-α, TNFRSF1A, IL-1β, IL-6, and IL-17A." (PMID 26245758, 2015). "IL-6, IL-1β, and TNF-α are all important cytokines that stimulate RASFs and inflammatory cells to aggravate synovial inflammation, resulting in joint destruction." (PMID 26303122, 2015). "Consistent with BML-111-induced downregulation of the TLR2/MyD88/NF-κB pathway, the OVA-induced airway inflammation was restrained, as shown by the reduced serum levels of IL-1β, IL-4 and IL-8, as well as BALF levels of IL-1β, IL-4, IL-8, OVA-IgE." (PMID 25760938, 2015).
inflammation (continued). "In particular, the synergistic action of Sup and Pre, components of PM2.5, can elicit airway inflammation by the elevation of eosinophils in BALF, Th2-type immunoresponse and the activation of inflammasome such as IL-1β." (PMID 24671176, 2014). "In contrast to our findings, pulmonary inflammation as assessed by TNF-α, KC, IL-1β, and MIP-2 levels and histologic score is reduced in Nlrc4−/− mice infected with K. pneumoniae." (PMID 25232720, 2014). "In contrast, high dose IT IL-6 resulted in marked anti-inflammatory effects as judged by reduced BAL fluid cytokines (IL-6, CXCL1, TNF-α), lung inflammation (IL-6, CXCL1, IL-1β), and serum CXCL1." (PMID 23667439, 2013). "Cows with persistent uterine inflammation had higher serum concentrations of adiponectin, TNF-α, IL-1β and IL-6 compared to normal and recovered cows." (PMID 24209779, 2013). "Viral titer, airways inflammation, superoxide and peroxynitrite production, lung histopathology, pro-inflammatory (MCP-1) and antiviral (IL-1β) cytokines/chemokines, CD8+ T cell effector function and alveolar epithelial cell apoptosis were assessed." (PMID 21304882, 2011). "On a related note we have previously reported high correlation between the degree of particle exposure related acute lung inflammation (PMN numbers) and IL1B BAL concentrations in mice." (PMID 19954533, 2009). "In the present study, S. aureus significantly elevated IL-1β expression (p < 0.05) and TNF-α expression of (p < 0.01) in the mammary gland, indicating the occurrence of mammary inflammation, while L. plantarum X86 inhibited the expression of these two cytokines to varying degrees." (PMID 40129572, 2025). "Chronic intestinal inflammation in IBD is driven in part by elevated pro-inflammatory cytokines such as TNF-α, IL-6, IL-17, IL-1β, and IFN-γ, which collectively promote leukocyte recruitment, amplify epithelial injury, and sustain a feed-forward inflammatory loop." (PMID 41333470, 2025). "Besides neurogenic inflammation, virus-induced airway inflammation and the accompanying release of cytokines, such as IFN-γ, TNF-α, or IL-1β, are known to demonstrate an impact on airway hypersensitivity and, therefore, an increase in coughing." (PMID 40722746, 2025). "The analysis of mRNA expression revealed that TNF-α, IL-1β, and IL-6 levels were higher in the colons of the HFV group, when compared with those of the NDV group, indicating high-fat/calorie diet-induced gut inflammation." (PMID 40284250, 2025). "Similarly, interleukin-1 beta (IL-1β) plays a crucial role in chronic vascular inflammation, with studies like the CANTOS demonstrating that IL-1β inhibition can significantly reduce cardiovascular events." (PMID 40217801, 2025). "Curcumin and its derivatives exert their effects by inhibiting the NF-κB signaling pathway, which downregulates pro-inflammatory factors such as COX-2, JNK, PI3K, and AP-1, thereby reducing the secretion of pro-inflammatory mediators like IL-6, IL-1β, TNF-α, and alleviating joint inflammation." (PMID 40806131, 2025). "Furthermore, by targeting NF-κB/NLRP3/IL-1β signaling, TRL mitigated bleomycin-induced pulmonary inflammation and fibrosis." (PMID 40698661, 2025). "A similar effect was exhibited in this study; we found that PF significantly decreased the release of TNF-α and IL-1β in the serum of LPS-administrated rats and prevented cardiac inflammation, as illustrated by the reduction of TNF-α and IL-1β in cardiac tissue." (PMID 41311552, 2025). "However, our group previously shown that MQEO had protective effect against intestinal inflammation in vivo and in vitro with potent anti-inflammatory properties via suppression of TNF-α and IL-1β." (PMID 38655301, 2024). "Analysis of bacterial species composition and KEGG function showed that high-dose intragastric PM leads to colonic intestinal inflammation by increasing the abundance of various bacteria in the jejunum, ileum, and colon and increasing the levels of LBP and IL-1β." (PMID 38535466, 2024).
inflammation (continued). "Combined with the correlation analysis that PIEZO1 expression was positively correlated with inflammatory mediators, IL-1β, TNF-α, and IL-6, it is speculated that PIEZO1 might play a vital role in the development of pulpal inflammation." (PMID 38627713, 2024). "Lung inflammation has also been shown to occur in rats after CuO NM instillation in addition to increased LDH and total protein level in BALF 24 h after exposure, and elevated concentrations of IL-1β, MIP-2 and MCP-1." (PMID 36650530, 2023). "Studies have shown that drugs can reduce the levels of IL-6 and IL-1β by inhibiting STAT3 expression, thereby ameliorating liver inflammation; targeting the STAT3 signaling pathway is considered an attractive therapeutic strategy for the development of anti-inflammatory drugs." (PMID 37165407, 2023). "Studies have shown that the expression of pro-inflammatory cytokines (such as IL-1β, IL-6, TNF-α, etc.)is significantly increased during intestinal inflammation, leading to a significant increase in intestinal epithelial tight-junction barrier permeability as a result of multiple effects." (PMID 37240380, 2023). "Moreover, IL-1β and TNF-α have been indicated to play a prominent role in the development of AHR and neutrophilic airway inflammation." (PMID 36803977, 2023). "The authors concluded that up-regulated IL-33 levels may facilitate lung inflammation by promoting the production of a range of innate pro-inflammatory cytokines, including TNF-α, IL-1β, IL-6, IL-12, IL-23." (PMID 36875710, 2023). "Furthermore, FD inhibits BLM-induced lung inflammation and fibrosis in mice via the activation of the NALP3 inflammasome and inhibition of the IL-1β/IL-1R1/ MyD88/NF-κB pathway." (PMID 36834561, 2023). "Significant changes in inflammatory and endothelium-specific variables IL-1β, IL-6, TNFα, oxLDL, H2O2, NO, 3-nitrotyrosine, and endothelial progenitor cells (OR 7.61, 95% CI 2.56–29.05, p < 0.0001), confirmed their interplay in vascular inflammation." (PMID 36362055, 2022). "LPS challenge induced liver inflammation and NASH-like pathological features by increasing ER stress and activating the caspase-11 non-canonical inflammasome, leading to subsequent hepatocyte pyroptosis and IL-1β secretion in obese mice." (PMID 35563377, 2022). "Over the course of 7 days, DSS-treated TRPV1-hM4Di mice developed intestinal inflammation characterized by a slight decrease in the body weight, increase in macroscopic damages and production of pro-inflammatory cytokines TNF-α, IL1-β, and IL-6." (PMID 34954381, 2022). "IL-1β and TNF-α are potent inflammatory mediators with endocrine effects in chronic inflammation." (PMID 36232665, 2022). "In addition, in a mouse model of lung inflammation, EGFR signaling and the NLRP inflammasome directly increase IL-1β levels." (PMID 36341365, 2022). "However, we unexpectedly found that trehalose, a natural sugar with pro‐autophagic activity, alleviates eosinophilic sinonasal inflammation and ECRS pathogenesis independently of autophagy via a preferential effect on the macrophage production of IL‐1β." (PMID 35988262, 2022). "The elevated levels of proinflammatory cytokines, such as IL-1β, TNF-α, and COX-2, could aggravate the progression of RA and could contribute to synovial inflammation and cartilage damage." (PMID 35401173, 2022). "In the current study, we show for the first time that TLR9−/− mice exhibit a low bone mass and low-grade systemic chronic inflammation, which is characterized by the expansion of CD4+ T cells and increased levels of inflammatory cytokines, including TNFα, RANKL, and IL1β." (PMID 35624094, 2022). "Chronic inflammation is a major factor affecting the ovarian microenvironment in patients with PCOS inducing higher ovarian androgen production, which involves two pro-inflammatory cytokines, interleukin-1 beta (IL-1β), and tumor necrosis factor (TNF-α)." (PMID 34233746, 2021).